MPC2 (mitochondrial pyruvate carrier 2)
Description:
Mediates the uptake of pyruvate into mitochondria to maintain the balance between glycolysis and oxidative phosphorylation. Plays an essential role in cellular metabolism.
Synonyms: BRP44; DKFZP564B167; SLC54A2
Tractability: Small molecule: a structure with a bound ligand is known; a high-quality ligand is known. Antibody: UniProt predicts a signal peptide or a membrane-spanning region. PROTAC: ubiquitination databases record sites on it; its protein half-life has been measured; a small molecule that binds it is known.
Target class: Mitochondrial pyruvate carrier family; Transporter; Electrochemical transporter
Gene: Protein-coding gene on chromosome 1 (167,916,675 to 167,937,502, reverse strand). Ensembl gene ENSG00000143158.
Subcellular location: Mitochondrion inner membrane
Pathways (Reactome):
Metabolism: Pyruvate metabolism
Gene Ontology:
Molecular function: identical protein binding; protein binding; pyruvate transmembrane transporter activity
Biological process: pyruvate import into mitochondria
Cellular component: inner mitochondrial membrane protein complex; mitochondrial inner membrane; mitochondrial pyruvate carrier complex; mitochondrion; nucleus
Genetic constraint (gnomAD): Loss-of-function variants: 5 observed, 9.15 expected, observed/expected ratio (o/e) 0.55, 90% interval 0.28 to 1.15. That is too few expected variants to judge how well the gene tolerates losing a copy. Missense variants: 95 observed, 108.24 expected, observed/expected ratio (o/e) 0.88, 90% interval 0.74 to 1.04. Synonymous variants: 49 observed, 39.93 expected, observed/expected ratio (o/e) 1.23, 90% interval 0.98 to 1.56.
Homologues: Orthologues: chimpanzee MPC2 (100% identical), macaque MPC2 (99% identical), pig MPC2 (97% identical), guinea pig MPC2 (95% identical), mouse Mpc2 (92% identical), rat Mpc2 (91% identical), dog MPC2 (89% identical), tropical clawed frog mpc2 (83% identical), zebrafish mpc2b (76% identical), zebrafish mpc2a (72% identical), Drosophila melanogaster CG9399 (54% identical), Caenorhabditis elegans mpc-2 (52% identical), and 2 more. Paralogues in human: MPC1 (24% identical), MPC1L (24% identical).
Diseases named in the same sentence as MPC2 in open-access papers:
MPC2 is named in the same sentence as 55 diseases in open-access papers, as found by Europe PMC text mining. Sharing a sentence is not in itself a finding about the gene and the disease. The quoted sentences say what the papers report.
prostate carcinoma (8 papers, 2015 to 2023). A carcinoma that arises from epithelial cells of the prostate gland. "The MPC1 and MPC2 variants and their potential molecular and biological functions in human prostate carcinoma are currently under investigation in our laboratory." (PMID 27852261, 2016). "Prostate cancer exhibited abundant MPC2, which was higher in patients with PCa than in controls, according to RNA-Seq data." (PMID 35972052, 2022). "An increasing number of studies showed downregulated expression of the MPC complex in different cancers, such as prostate cancer and hepatocellular carcinoma, and restoring MPC2 in human tumor cells inhibited melanoma cell proliferation and migration." (PMID 33791391, 2021). "In the present study, we have demonstrated the mitochondrial location of both MPC1 and MPC2 proteins in the WT prostate cancer cells by IF and Western blotting." (PMID 28624784, 2017). "Firstly, we detected MPC1 and MPC2 expression in the two human prostate cancer cell lines by ICC and Western blotting, confirming the different expressions of MPC1 and MPC2 in various histological subtype derived cell lines." (PMID 27852261, 2016). "ICC identified variable MPC1 and MPC2 protein expressions in the prostate cancer cell lines LNCaP and DU145." (PMID 27852261, 2016). "Linear regression analysis revealed that MPC1 expression level was positively correlated with MPC2 expression (r = 0.375, P = 0.006) in the prostate cancers." (PMID 27852261, 2016). "MPC1 and MPC2 gene expressions were assessed in prostatic cancer cell lines LnCap, DU145 and PC3 firstly in our lab, and it was found that LnCap exhibited higher expression levels of MPC1 and MPC2 compared to DU145 and PC3 (Data not shown)." (PMID 26413751, 2015). "In addition, another research reported that the MPC2 level was lower in prostate cancer cells and tissue, and MPC2 predicted a better OS of patients with prostate cancer." (PMID 33791391, 2021). "The reason might be that prostate cancer cells already have elevated expression of endogenous MPC2, which could form functional transporter complexes with the ectopically expressed MPC1." (PMID 26895100, 2016). "However, the expression status of MPC1 and MPC2 in prostate cancer (PCA) is unclear." (PMID 27852261, 2016). "In this study, expression of MPC1 and MPC2 in LNCaP and DU145 prostate cancer cell lines was examined by immunocytochemistry (ICC) and Western blotting." (PMID 27852261, 2016). "Alternately, there is a cell type specific difference in MPC1/MPC2 stability, since we also found that when MPC1 was knocked down, MPC2 expression remained unchanged in prostate cancer cells, suggesting the complexity of the MPC transporter." (PMID 26895100, 2016). "In this study, we verified variable MPC1 and MPC2 expressions in two different prostate cancer cell lines (LNCaP and DU145) and found that the aggressive DU-145 cell line expressed lower levels of MPC1 and MPC2." (PMID 27852261, 2016). "In conclusion, we have found low expression of MPC1 and MPC2 in agressive prostate cancer cell line, and also discovered that negative expression of MPC complex is significantly associated with unfavorable clinicopathological features in PCA samples and shorter survival in PCA patients." (PMID 27852261, 2016).
colorectal cancer (6 papers, 2015 to 2023). A primary or metastatic malignant neoplasm that affects the colon or rectum. "This study was conducted with the aim of exploring the role and underlying mechanisms of MPC2 in colorectal cancer (CRC)." (PMID 33791391, 2021). "MPC1 and MPC2 gene expression has been investigated in cell lines like embryonal, heatologic, ovarian and colorectal cancer cell lines." (PMID 26413751, 2015). "The downregulation of MPC2 promotes glycolysis via the mTOR pathway in colorectal cancer cells." (PMID 37147584, 2023). "Studies have shown that when overexpressing either MPC1 or MPC2 by itself in colorectal cancer cells, the protein fails to accumulate to a high level, suggesting that these two proteins might need to form a complex to be stable." (PMID 27852261, 2016).
schizophrenia (4 papers, 2018 to 2020). A major psychotic disorder characterized by abnormalities in the perception or expression of reality. "This situation holds for genes such as MPC2, associated with schizophrenia, SYCP3, with azoospermia, and NAT8, with chronic kidney disease." (PMID 32392208, 2020). "Previous genome-wide association studies (GWAS) suggest that rs10489202 in the intron of MPC2 (mitochondrial pyruvate carrier 2) is a risk locus for schizophrenia in Han Chinese populations." (PMID 30087317, 2018). "The situation is even more complex in the case of MPC2, CLC, and HIST1H2AC, which are all associated with schizophrenia." (PMID 32392208, 2020). "Recent GWAS and meta-analysis in East Asian population showed MPC2 variant rs10489202 may be a risk locus for schizophrenia, indicating that expression of MPC2 may play a role in pathogenesis of schizophrenia." (PMID 32565801, 2020). "The PGC schizophrenia GWA study did not identify MPC2 as a significant locus but in our Asian only meta-analyses we found a robust association between this gene and schizophrenia." (PMID 31455759, 2019). "In the present study, we have conducted association analyses of three SNPs (rs10489202 and two additional SNPs rs9618 and rs203863) in the MPC2 region in 437 schizophrenia cases and 2031 controls from Southern Han Chinese populations (these samples were not included in previous studies of the gene)." (PMID 30087317, 2018). "CAMK2D, EIF3K, MPC2, MYL12B, PAM, and SLC35B4, selected from the schizophrenia dataset and TCGA, were reevaluated in CGGA through gene expression in glioma grading and survival curves between patients having high level of gene expression and those having low level of gene expression." (PMID 32565801, 2020). "Although the MPC2 gene is not related to the tested SNPs in the current eQTL analyses, our data do not deny the possibility that this gene and even other genes in the genomic region could be involved in schizophrenia." (PMID 30087317, 2018). "Combined data from five Asian schizophrenia GWA studies (14, 433 cases and 26, 797 controls) and applicable Asian candidate-gene studies revealed two Bonferroni-significant LD-independent loci (CNNM2, MPC2) not identified in our candidate gene only meta-analyses." (PMID 31455759, 2019).
glioma (2 papers, 2020 to 2021). A benign or malignant brain and spinal cord tumor that arises from glial cells (astrocytes, oligodendrocytes, ependymal cells). "A recent study found that the MPC2 mRNA level predicted a worsened survival in patients with isocitrate dehydrogenase-mutant glioma using an online database." (PMID 33791391, 2021). "Moreover, a study showed that MPC2 predicted poor survival in patients with isocitrate dehydrogenase-mutant glioma, although the potential role of MPC2 in cancer, the clinical relevance, and molecular mechanism underlying its influence on CRC progression remain unknown." (PMID 33791391, 2021).
acute kidney injury (1 paper, 2024). Sudden and sustained deterioration of the kidney function characterized by decreased glomerular filtration rate, increased serum creatinine or oliguria. "The specific role of MPC2 in acute kidney injury is not yet clear." (PMID 39247825, 2024).
Alzheimer disease (1 paper, 2021). A progressive, neurodegenerative disease characterized by loss of function and death of nerve cells in several areas of the brain leading to loss of cognitive function such as memory and language. "A decrease in MPC2 expression in Alzheimer's disease models is associated with less Ca2+ uptake, and studies in hepatocytes and embryonic fibroblasts have shown the Ca2+ import into mitochondria is also decreased following inhibition of MPC activity." (PMID 33824204, 2021). "It has also been reported that decreased expression of MPC2 in Alzheimer’s disease-related models led to decreased Ca2+ and pyruvate uptake into mitochondria and reduced Ca2+-mediated stimulation of the TCA cycle, although the reason for the decrease in Ca2+ import was unknown." (PMID 33824204, 2021).
asthma (1 paper, 2025). "In an ovalbumin (OVA)-induced asthma model, conditional deletion of Mpc2-but not Ldha-in club cells impaired club-to-goblet cell differentiation, reduced CLCA3 and Foxa3 expression, and attenuated eosinophilic inflammation and Il-13 expression." (PMID 41418787, 2025).
bladder cancer (1 paper, 2015). "The structural resemblance of 3-BrPA to pyruvate and lactate impelled us to examine the contribution of MCT1, MCT4 and SMCT1 plasma-membrane monocarboxylate transporters, as well as MPC1 and MPC2 mitochondrial pyruvate carrier components, to bladder cancer cell responsiveness to 3-BrPA." (PMID 26198749, 2015).
breast carcinoma (1 paper, 2024). "Downregulation of MPC1 or MPC2 has been observed in several types of human cancers such as kidney, cholangiocarcinoma and breast cancer." (PMID 38615083, 2024).
Breast Invasive Carcinoma (1 paper, 2018). "In particular, we analyzed the MPC2/MPC1 expression ratio in normal and cancer tissues from the Breast Invasive Carcinoma (BRCA) dataset publicly available at The Cancer Genome Atlas project." (PMID 29472561, 2018).
breast tumors (1 paper, 2018). "Altogether, a shifted MPC2/MPC1 ratio in breast tumors may have an impact on respiratory metabolism which could lead to increase in the mitochondrial pyruvate oxidative metabolism." (PMID 29472561, 2018).
cardiac hypertrophy (1 paper, 2021). "Downregulation of MPC1 and MPC2 was observed in failing human hearts and in mouse models of pathological cardiac hypertrophy." (PMID 33473180, 2021).
colon adenocarcinoma (1 paper, 2017). "We also looked at other genes involved in pyruvate transport and metabolism and interestingly, MPC1, MPC2, PDHA1 and PC showed consistent downregulation in a specific subset of colon adenocarcinomas known as colon mucinous adenocarcinomas (AC) (n = 22)." (PMID 28397687, 2017).
colon cancer (1 paper, 2024). "For example, it was reported in colon cancer that both expressions of MPC1 and MPC2 are decreased in tumor tissues as compared with normal counterparts." (PMID 38615083, 2024).
diabetes (1 paper, 2026). "This study establishes MPC2-mediated mitochondrial functional repair as a core mechanism through which microbial metabolites regulate enteroendocrine hormone secretion, identifying a novel therapeutic target within the "gut-islet axis" for diabetes intervention." (PMID 41704276, 2026).
diabetic nephropathy (1 paper, 2020). "Renal tubule MPC1 and MPC2 protein expression were significantly lower in diabetic nephropathy patients compared to patients with non-diabetic kidney disease." (PMID 32784379, 2020).
esophageal squamous cell carcinoma (1 paper, 2017). Esophageal squamous cell carcinoma (ESCC) is a type of esophageal carcinoma (EC) that can affect any part of the esophagus, but is usually located in the upper or middle third. "In addition, we also determined the expression status of MPC1 and MPC2 in a series of 157 esophageal squamous cell carcinomas and found that the low expression of MPC1 predicted an unfavorable outcome, indicating the regulation of metabolic reprogramming by MPC1 is pivotal for tumor cell growth." (PMID 27911865, 2017).
heart failure (1 paper, 2019). Inability of the heart to pump blood at an adequate rate to meet tissue metabolic requirements. "Future work to elucidate mechanisms of altered expression and function for MPC1, MPC2, and PDK isoforms and their adaptations in heart failure progression will be valuable in the setting of mitochondrial energy regulation and the development of clinically viable novel drugs for these targets." (PMID 30881593, 2019).
Hepatic steatosis (1 paper, 2025). Steatosis is a term used to denote lipid accumulation within hepatocytes. "Mice with conditional, HSC-specific MPC2 deletion were generated and their phenotypes assessed in the context of diets that cause hepatic steatosis, injury, and early-stage fibrosis." (PMID 40239806, 2025). "In line with our in vitro findings, we found that mice with stellate cell-specific deletion of Mpc2 had attenuated liver pathology in response to MASH-inducing diets that was independent of a change in hepatic steatosis." (PMID 40239806, 2025).
hepatocellular carcinoma (1 paper, 2025). A malignant tumor that arises from hepatocytes. "We engineered HepG2 cells, which were originally isolated from a hepatocellular carcinoma, to express epitope-tagged MPC1 and MPC2 in a doxycycline-inducible manner." (PMID 41400249, 2025).
Hyperglycemia (1 paper, 2020). An increased concentration of glucose in the blood. "In the liver, Mpc1 or Mpc2 knockout decreases hepatic gluconeogenesis and attenuates hyperglycemia in high-fat-diet-induced or leptin-receptor-deficient (db/db) mice without causing hypoglycemia in lean, normal chow-fed mice." (PMID 32784379, 2020). "In a high-glucose cell culture model designed to mimic T2D hyperglycemia, MPC chemical inhibition and siRNA knockdown of MPC2 in podocytes induced mitochondrial damage and increased apoptosis." (PMID 32784379, 2020).
Hypoglycemia (1 paper, 2024). A decreased concentration of glucose in the blood. "In conclusion, combined deletion of Mpc2 and Gpt2 in liver of mice markedly impairs hepatic gluconeogenesis and leads to hypoglycemia, hyperlactatemia, and reduced exercise performance in a graded intensity treadmill protocol." (PMID 38353639, 2024).
Immunodeficiency (1 paper, 2023). Failure of the immune system to protect the body adequately from infection, due to the absence or insufficiency of some component process or substance. "Strikingly, the best contributor genes to MPC2 involved TREM2/TYROBP, an axis associated with immunosuppression, suggesting that MPC2 might correspond to tumor associated macrophage (TAM) infiltrates despite the immunodeficiency of NSG mice." (PMID 37377921, 2023).
liver disease (1 paper, 2025). "Interestingly, expression of Spp1, the gene encoding osteopontin and associated with more advanced liver disease progression, seemed to be decreased in multiple clusters including monocytes, transitioning monocytes, C-LAMs, and LAMs in Lrat-Mpc2-/- mice compared with WT mice." (PMID 40239806, 2025).
lung adenocarcinoma (1 paper, 2020). A carcinoma that arises from the lung and is characterized by the presence of malignant glandular epithelial cells. "The expression of MPC1 was significantly upregulated in the cholesterogenic group in KIRC, LGG, lung adenocarcinoma (LUAD) and LUSC, and the expression of MPC2 was significantly upregulated in the cholesterogenic group in PAAD, sarcoma (SARC) and CESC, similar to our findings in HCC." (PMID 32479426, 2020).
lymph node metastasis (1 paper, 2016). "The MPC2 protein expression was negatively associated with lymph node metastasis, and 13 out of the 14 (92.86%) tumors with lymph node metastases were either weakly positive or negative for the protein." (PMID 27852261, 2016). "While UICC stage (P < 0.001) and lymph node metastasis (P = 0.002) were negatively associated with MPC2 expression." (PMID 27852261, 2016). "Our study shows that tumor tissue MPC2 expression is inversely correlated with the following PCA clinicopathologic characteristics like UICC stage and lymph node metastasis, while MPC1 expression is inversely correlated with the UICC stage." (PMID 27852261, 2016).
lymphoma (1 paper, 2025). A malignant (clonal) proliferation of B- lymphocytes or T- lymphocytes which involves the lymph nodes, bone marrow and/or extranodal sites. "This study provides new insights into the metabolic reprogramming of DLBCL and suggests MPC2 as a potential therapeutic target for this aggressive lymphoma." (PMID 40287899, 2025).
malaria (1 paper, 2024). Malaria is a serious and sometimes fatal disease caused by a parasite that commonly infects a certain type of mosquito which feeds on humans. "A previous study demonstrated that artemether (Art), an artemisinin derivative applied in the treatment option for malaria, could protect against kidney injury in T2D db/db mice partially via increasing MPC1 and MPC2 levels." (PMID 39247825, 2024).
myeloma (1 paper, 2023). "In addition, MDH2, MPC2, PAXIP1, and NSDHL were upregulated in myeloma patients." (PMID 37333985, 2023).
myeloproliferative disorder (1 paper, 2023). A clonal hematopoietic stem cell disorder, characterized by proliferation in the bone marrow of one or more of the myeloid (i.e., granulocytic, erythroid, megakaryocytic, and mast cell) lineages. "Thus, MPC2-deficient myeloid cells did not continue to outcompete their WT competitors at later time points, which otherwise would have led to a myeloproliferative disorder." (PMID 37249600, 2023).
neuroendocrine tumours (1 paper, 2023). "However, MPC2 RNA abundance is significantly decreased in neuroendocrine tumours compared with adenocarcinoma tumours." (PMID 38049604, 2023).
ovarian carcinoma (1 paper, 2021). A malignant neoplasm originating from the surface ovarian epithelium. "Among 614 women with ovarian cancer cases followed over 20 years, we found that relative to those with high MPC2 gene expression, low MPC expression was associated with a 59% increase in mortality (p < 0.0001), suggesting that mitochondrial metabolism contributes to ovarian tumor biology in humans." (PMID 34078919, 2021).